CEACAM1 (CEA cell adhesion molecule 1)
Diseases named in the same sentence as CEACAM1 in open-access papers (continued):
Sharing a sentence is not in itself a finding about the gene and the disease.
lung adenocarcinoma (8 papers, 2006 to 2024). A carcinoma that arises from the lung and is characterized by the presence of malignant glandular epithelial cells. "CEACAM1 has been described as a lung tumor marker, and its expression has been associated with the prognosis of lung adenocarcinoma." (PMID 20525254, 2010). "Here we demonstrate that cell surface expression of CEACAM1 on confluent A549 human lung adenocarcinoma cells plays a critical role in differentiated, contact-inhibited cell growth." (PMID 20090913, 2010). "Previous studies reported the independent prognosticator role of CEACAM1 in lung adenocarcinoma." (PMID 35178154, 2022). "Although other CEACAM family proteins, such as CEACAM1 and CEACAM5, are known to be dysregulated in lung adenocarcinoma as well, CEACAM6 is more highly expressed than CEACAM5 and is associated with poor clinical outcomes among lung adenocarcinoma patients." (PMID 31474761, 2019). "Previously it was found that the survival of CEACAM1-negative lung adenocarcinoma patients was significantly longer than that of CEACAM1-positive patients." (PMID 39513107, 2024).
thyroid cancer (8 papers, 2010 to 2021). "Taken together, our results show that M2 macrophage markers and TIM3/galectin-9/CEACAM1 expression levels are increased in thyroid cancer tissues, thereby supporting our in vitro findings." (PMID 34638305, 2021). "For example, in thyroid cancer, expression of CEACAM1, a molecule also involved in both adhesion and cell signaling for growth pathways, facilitated invasion but slowed growth of tumor xenografts." (PMID 20074368, 2010). "In addition, overexpression of CEACAM1 in thyroid cancer cells results in increased cell invasion and migration, while CEACAM1 knockdown improved cell growth but decreased cell invasiveness." (PMID 30296284, 2018). "CEACAM1 is not appreciably expressed in normal human thyroid tissue and is rarely present in benign tumors but highly upregulated in thyroid carcinomas, especially in metastatic tumors." (PMID 30406153, 2018).
autoimmune disease (7 papers, 2007 to 2025). A disorder resulting from loss of function or tissue destruction of an organ or multiple organs, arising from humoral or cellular immune responses of the individual to their own tissue constituents. "Correspondingly, CEACAM1 is highly induced on Tregs from patients with autoimmune disease undergoing low-dose IL-2 therapy, and these Tregs showed reduced proliferation." (PMID 40773294, 2025). "Findings suggest that CEACAM1 (gene X16354) participates in immune regulation in physiological conditions and in pathological conditions, such as inflammation, autoimmune disease, and cancer." (PMID 17316436, 2007). "However, very few studies have investigated the role of CEACAM1 in regulating autoimmunity in human autoimmune diseases." (PMID 36591283, 2022). "However, despite substantial CEACAM1 expression levels on normal B-cells, Ceacam1-deficient mice do not develop autoimmune disease; instead, they have significantly reduced rather than increased numbers of B cells." (PMID 40436855, 2025). "The variable induction of CEACAM1 in Tregs by low-dose IL-2 was not resolved when considering each autoimmune disease separately." (PMID 40773294, 2025). "Following this line, serum CEACAM1 concentrations were not elevated in patients with an autoimmune disease like SLE, suggesting on disease specific mechanisms among inflammatory conditions." (PMID 26909604, 2016).
diabetes (7 papers, 2011 to 2026). "That this occurs independently of diabetes and fasting hyperglycemia is consistent with normal insulin secretion and fasting normoglycemia in Ceacam1 mutant mice." (PMID 28396653, 2017). "CEACAM1 expression was downregulated in diabetes mellitus and high-fat diet mouse model, therefore, controlling diet to maintain glucose and lipid metabolism balance might be also a potential therapeutic strategy in RPL." (PMID 40046057, 2025). "We constructed a diabetes mellitus (DM) + high-fat diet (HFD) mouse model based on the streptozotocin (STZ)-induced apolipoprotein E-knockdown (ApopE−/−) mouse to investigate the roles and regulatory mechanism of miR-449a/CEACAM1 axis." (PMID 38715117, 2024). "While the function of the CEACAM1 in diabetes facilitates plaque formation remains not entirely understood." (PMID 38715117, 2024). "In conclusion, the CEACAM1 expression was decreased in the liver of severely obese patients with or without diabetes." (PMID 21569294, 2011). "The CEACAM1 expression was evaluated immunohistochemically in the liver tissues of 99 severely obese or non-obese subjects with or without diabetes." (PMID 21569294, 2011). "However, the relation between decreased CEACAM1 expression and diabetes was not supported in this study." (PMID 21569294, 2011).
metastatic melanoma (7 papers, 2012 to 2025). A melanoma that has spread from its primary site to another anatomic site. "CEACAM1 expression in normal melanocytes is scant, but is increased with tumor progression and it is overexpressed in most cases of metastatic melanoma." (PMID 26885752, 2016). "Kluger's group also showed that plasma CEACAM1 is elevated in patients with metastatic melanoma compared to healthy controls and early stage disease." (PMID 27642217, 2016). "The wide distribution of CEACAM1 in metastatic melanoma qualifies it for targeted therapy, alone or in combination." (PMID 27642217, 2016). "It should be noted that CEACAM1 is expressed in 60–80% of metastatic melanoma cases, which suggests that the majority of metastatic melanoma patients would benefit from anti-CEACAM1 antibodies." (PMID 22778766, 2012). "In addition, the CEACAM1 interactions seemed also to be important in some cases of metastatic melanoma, as increased CEACAM1 expression was observed on NK cells derived from such patients if compared with NK cells from healthy donors." (PMID 30871206, 2019). "In metastatic melanoma, the level of soluble CEACAM1 significantly correlated with LDH level." (PMID 27642217, 2016). "The high serum CEACAM1 levels observed in metastatic melanoma patients is irrespective of neoplastic pericardial involvement, implying that different patho-physiological mechanisms account for the enhanced serum CEACAM1 in pericarditis patients." (PMID 26909604, 2016). "Serum CEACAM1, MICA and MICB concentrations were measured by ELISA in ∼50 subjects of each group: acute pericarditis (AP), recurrent pericarditis (RP) and lupus (SLE) patients, metastatic melanoma patients as well as healthy donors." (PMID 26909604, 2016).
steatosis (7 papers, 2011 to 2025). Increased lipid within the cytoplasm of cells. "Consistently, deleting CEACAM1 from hepatocytes caused steatosis and visceral obesity, both of which could partially alter the inflammatory milieu of the liver through the release of IL-6 among other interleukins." (PMID 39640841, 2024). "Interestingly, high-fat feeding causes a progressive NASH phenotype in global Ceacam1 null mice, including a higher degree of macro-steatosis in parenchyma, and more robust hepatic fibrosis and apoptosis." (PMID 36009446, 2022). "Interestingly, the hepatocytes with fatty change, and particularly those with macrovesicular steatosis, revealed the loss of a CEACAM1 expression." (PMID 21569294, 2011). "The CEACAM1 expression was lost mainly in the hepatocytes with fatty change, particularly macrovesicular steatosis." (PMID 21569294, 2011). "The CEACAM1 expression was markedly decreased in the hepatocytes with macrovesicular steatosis." (PMID 21569294, 2011). "The increase in steatosis, increased expression of CD36, SREBF1, and SCD1, and the decreased expression of CEACAM1 and GLUT2 are all key features also seen in our hyperglycemic HepG2 model as well as the Leprdb/J mouse model." (PMID 31805072, 2019). "In this study we addressed the hypothesis that drivers of insulin clearance, such as CEACAM‐1 and IDE, would be reduced in obese horses and ponies with fasting HI and that these would present steatosis." (PMID 40476757, 2025). "Of note, measures of insulin clearance (CEACAM‐1 gene expression, IDE activity) did not correlate with measures of steatosis (MASLD scale, steatosis score, liver TG content)." (PMID 40476757, 2025).
atherosclerosis (6 papers, 2019 to 2024). A disease characterized by the build-up of fatty material and calcium deposition in the arterial wall resulting in partial or complete occlusion of the arterial lumen. "Emerging evidence indicates carcinoembryonic antigen-related cell adhesion molecule 1 (CEACAM1) is involved in the development of atherosclerosis (AS)." (PMID 38715117, 2024). "CEACAM1 expression involves in vascular homeostasis in atherosclerosis." (PMID 38715117, 2024). "Nevertheless, whether miR-449a interacts with CEACAM1 to affect atherosclerosis progression remains unknown." (PMID 38715117, 2024). "Whether this drug can prevent atherosclerosis by inducing Ceacam1 transcription in endothelial cells and hepatocytes of patients with cardiovascular risk remains to be tested." (PMID 35457157, 2022). "For example, CEACAM1 is important for angiogenesis and is involved in endothelial homeostasis and dysfunction, i.e., processes that are part of the pathogenesis of both atherosclerosis and psoriasis." (PMID 34639156, 2021). "Our data suggest that CEACAM1 might represent an attractive target in order to delay physiological aging and therefore the transition to vascular disorders such as atherosclerosis." (PMID 31389127, 2019). "In angiogenesis, CEACAM1 stimulates the proliferation, chemotaxis, and capillary-like tube formation of human microvascular endothelial cells, prompting further exploration into the angiogenic properties of CEACAM1 as treatment towards vascular diseases, such as atherosclerosis." (PMID 36741860, 2023). "Some of these CEACAM1‐dependent effects, that is, increased oxidative stress, increased VEGF/VEGFR‐2 signaling, and increased endothelial permeability, may render aged blood vessels prone to the onset of vascular disorders such as atherosclerosis in the presence of additional risk factors." (PMID 31389127, 2019).
COVID-19 (6 papers, 2021 to 2025). A disease caused by infection with severe acute respiratory syndrome coronavirus 2. "A significant increase in the number of developing neutrophils was found in COVID-19 while CEACAM1, CEACAM6 and CEACAM8 were also significantly co-localized developing neutrophils." (PMID 34217339, 2021). "After assembling its PPIs, 11 PPI partners (e.g., CEACAM1 and STAT3) were added to this network and salmeterol was computationally predicted to show noticeable correlations on COVID-19 (Z = −2.86, p < 10–5)." (PMID 34539756, 2021). "Studies have also shown that compared with controls, the lung tissue of patients who died of COVID-19 had upregulated expression of proteins such as NPC1/2, CEACAM1, CTSL, EIF4E, and PABPN1, which involve virus-binding receptors, proteases, host mRNA degradation, and translation cessation." (PMID 38752128, 2024).
endothelial dysfunction (6 papers, 2019 to 2025). In vascular diseases, endothelial dysfunction is a systemic pathological state of the endothelium (the inner lining of blood vessels) and can be broadly defined as an imbalance between vasodilating and vasoconstricting substances produced by (or acting on) the endothelium. "CEACAM1 is critical for aging‐associated vascular alterations like endothelial dysfunction, fibrosis, oxidative stress, and sustained inflammation and can be regarded as a main contributor to vascular inflammaging." (PMID 39434463, 2025). "Upregulation of CEACAM1 inhibited inflammation, promoted plaque stability in vivo, and suppressed endothelial dysfunction in vitro." (PMID 38715117, 2024). "CEACAM1 contributes to aging-related vascular disorders such as endothelial dysfunction and atherosclerotic plaque formation via collagen depositions." (PMID 38715117, 2024). "However, in the present study, the limitations will not affect the results and conclusion that miR-449a promotes atherosclerotic plaque rupture, inflammation, and endothelial dysfunction by interacting with CEACAM1." (PMID 38715117, 2024). "Loss of endothelial Ceacam1 gene caused endothelial dysfunction and reduced vascular integrity without affecting systemic insulin sensitivity." (PMID 35457157, 2022). "Moreover, to further explore whether miR-449a affected endothelial dysfunction via targeting CEACAM1 in vitro." (PMID 38715117, 2024). "Consequently, aging‐related upregulation of vascular CEACAM1 expression results in endothelial dysfunction that may promote atherosclerotic plaque formation in the presence of additional risk factors." (PMID 31389127, 2019).
inflammatory bowel disease (6 papers, 2011 to 2022). A spectrum of small and large bowel inflammatory diseases of unknown etiology. "Certain pathologic conditions (coeliac disease and inflammatory bowel disease) have previously been shown to cause increased CEACAM1 expression on T cells in the lamina propria of the gut." (PMID 23894299, 2013). "Previous studies suggest that Ceacam1 negatively regulates inflammation in inflammatory bowel disease models." (PMID 21760897, 2011). "CEACAM1 negatively regulates inflammation in inflammatory bowel disease models." (PMID 35982137, 2022). "Elevated CEACAM1 expression has been reported in T cells of the lamina propria of small intestine in patients with celiac disease and in the large intestine of those with inflammatory bowel disease (IBD)." (PMID 23521917, 2013). "TIM-3 is co-expressed with CEACAM1 during tolerance induction during chronic viral infection in inflammatory bowel disease (IBD) and in colon tumors." (PMID 30314283, 2018).
Stroke (6 papers, 2013 to 2024). Sudden impairment of blood flow to a part of the brain due to occlusion or rupture of an artery to the brain. "In a mouse stroke model, the presence of mouse CEACAM1 inhibits the MMP9-mediated damage to endothelial cells." (PMID 31849868, 2019). "Peter Ludewig from Tim Magnus` group studied the role of carcinoembryonic antigen-related cell adhesion molecule 1 (CEACAM-1) in experimental stroke." (PMID 24330587, 2013). "CEACAM1 controls the secretion of matrix metalloproteinase-9 by neutrophils in inflammatory sites after brain-deficient stroke, thereby protecting the function of BBB and improving the outcome after stroke." (PMID 34335600, 2021). "Therefore, CEACAM1 function may represent a potential target in order to delay unfavorable age‐dependent vascular alterations, thereby preventing the onset of transition from physiological aging into angiopathies with their secondary diseases such as myocardial infarction and stroke." (PMID 31389127, 2019).
colitis (5 papers, 2011 to 2023). Inflammation of the colon. "Mouse adoptive transfer colitis models show CEACAM1-deficient T cells to be hyperinflammatory with reduced cell surface expression of TIM-3 as well as regulatory cytokines, and this can be restored by T cell-specific CEACAM1 expression." (PMID 30406153, 2018). "The data suggest a protective role of CEACAM1 in models of colitis by modulating tissue and the immune environment." (PMID 36741860, 2023). "CEACAM1 expression also decreases intestinal permeability and increases epithelial barrier function in a murine model of colitis induced by dextran sulfate sodium (DSS), decreasing severity and symptomatology of the disease." (PMID 36741860, 2023). "The increase in expression of CD177 and CEACAM1, for instance, is closely related to colitis after ipilimumab treatment." (PMID 37304306, 2023). "Inhibition of CEACAM1 leads to a hyperinflammatory state that induces progression and worsens the presentation of colitis in murine models, nullifying the normal critical immunosuppressive effect of CEACAM1." (PMID 36741860, 2023). "In vivo, ligation of Ceacam1 with soluble ligands or over-expression of ITIM-containing Ceacam1 isoforms on T cells attenuates experimental colitis." (PMID 21760897, 2011).
lymph node metastasis (5 papers, 2014 to 2023). "Univariate analysis revealed that depth (>T3), lymph node metastasis, lymphatic permeation, venous permeation and non CEACAM1-expression were significant risk factors for peritoneal dissemination." (PMID 31481751, 2019). "Kaplan–Meier survival analysis revealed that high-density of CD15+ neutrophils, strong expression of CEACAM1, lymph node metastasis, high clinical stage and tumor recurrence were associated with shorter cancer-related survival of TSCC patients." (PMID 24587171, 2014). "CEACAM1 overexpression was also associated with lymph node metastasis (P = 0.000) and higher clinical stage (P = 0.001)." (PMID 24587171, 2014). "Increased CEACAM1 expression in GC is associated with such clinical characteristics as TNM stage and lymph node metastasis." (PMID 34943606, 2021). "Univariate analysis revealed that depth (>T3), lymph node metastasis, lymphatic permeation, venous permeation and non CEACAM1-expression were significant predictive factors for overall survival." (PMID 31481751, 2019). "On the basis of multivariate analysis, depth (>T3), lymph node metastasis and non CEACAM1-expression were selected as independent predictive factors for overall survival." (PMID 31481751, 2019). "At present, there are not enough studies on the association of CEACAM1 expression with survival in GC; however, increased CEACAM1 expression is most likely associated with the TNM stage and lymph node metastasis." (PMID 34943606, 2021). "Multivariate analysis demonstrated that lymph node metastasis, TIM-3+ TILs infiltration, and CEACAM1 expression were independent prognostic factors for OS, while lymph node metastasis and CEACAM1 expression could be regarded as independent prognostic factors of DFS (all p < 0.05)." (PMID 34368221, 2021).